HK2 (hexokinase 2)
Diseases named in the same sentence as HK2 in open-access papers (continued):
Sharing a sentence is not in itself a finding about the gene and the disease.
Insulin resistance (17 papers, 2017 to 2025). Increased resistance towards insulin, that is, diminished effectiveness of insulin in reducing blood glucose levels. "Similar HK2-linked unscheduled glycolysis in skeletal muscle and adipose tissue in impaired fasting glucose drives the development of peripheral insulin resistance." (PMID 38292764, 2023). "If HK2-linked unscheduled glycolysis contributes to insulin resistance, decreases in HK2 expression are expected to decrease insulin resistance and improve glucose tolerance." (PMID 35216280, 2022). "From the hypothesis of HK2-linked unscheduled glycolysis in the development of insulin resistance, two key predictions follow." (PMID 35216280, 2022). "In insulin resistance, HK2-linked unscheduled glycolysis may also be established in skeletal muscle and adipose tissue." (PMID 35216280, 2022). "The metabolic dysfunction characteristic of HK2-linked unscheduled glycolysis is found in insulin resistance in skeletal muscle: hyperpolarization of mitochondria and increased ROS formation, increased hexosamine pathway activity, and activation of PKC and dicarbonyl stress." (PMID 35216280, 2022). "Genes associated with energy metabolism (e.g., gapdh, tpi, pgk, and fbp) were upregulated, while hk2 was downregulated, potentially due to insulin resistance." (PMID 40362236, 2025). "To counter peripheral insulin resistance, we seek to inhibit HK2-mediated glucose metabolism in the skeletal muscle and adipose tissue in the fasting phase but not in the absorptive phase; therefore, direct chemical inhibitors of HK2 are undesirable." (PMID 38292764, 2023). "Overexpression of HK2 in the skeletal muscle induced insulin resistance in mice fed a high fat diet (HFD)." (PMID 38292764, 2023). "To explore the effect of insulin resistance on glycolysis, we detected the expression of key glycolytic enzymes (HK2, PKM2, and LDHA) in KGN cells after insulin treatment and RES intervention." (PMID 36742000, 2022). "Results showed down-regulation of insulin-responsive genes, HK2, EGR1, and CIDEC, which verify insulin resistance through deficiency of insulin signaling." (PMID 32831068, 2020). "Since expressions of insulin-regulated genes are positively correlated with insulin sensitivity, down-regulation of HK2, EGR1, and CIDEC genes in this group possibly verify insulin resistance through deficiency of insulin signaling." (PMID 32831068, 2020). "Research has shown that schistosomiasis affected the glucose metabolism of host, leading to the upregulation of glycolysis-related genes in the liver, such as Ldha, Glut4, Pkm2, Glut1, Pfkfb3, Aldoc, HK2, and Pfk and could also improve insulin resistance." (PMID 40152283, 2025). "Consistent with these previous findings, we observed that loss of adipose HK2 causes selective insulin resistance without affecting hepatic insulin signaling." (PMID 36920797, 2023). "From the hypothesized contribution of HK2-linked unscheduled glycolysis to the development of insulin resistance, the activation of the UPR provides a key contributory role, increasing the expression of established mediators of insulin resistance, TXNIP and tumor necrosis factor-α (TNFα)." (PMID 35216280, 2022). "However, the decrease in insulin sensitivity was not accompanied by a reduction of skeletal muscle insulin signaling or total protein amount of GLUT4 or hexokinase 2; but of course, insulin resistance could have been induced through other pathways that we did not investigate." (PMID 35619221, 2022). "A similar effect was found for peripheral insulin resistance in mice with transgenic overexpression of hexokinase-2 (HK2) on a HFD but not in mice with concurrent overexpression of GLUT1 and HK2." (PMID 41196673, 2025). "There is no indication of increased HK2 expression at the mRNA and protein level in the skeletal muscle and adipose tissues in clinical insulin resistance and some reports of decreases, likely due to decreased insulin-dependent expression." (PMID 38292764, 2023).
Insulin resistance (continued). "In diabetic individuals, miR-199a-5p may be involved in skeletal muscle insulin resistance by inhibiting glucose transporter 4 (GLUT4) and hexokinase 2 (HK2)." (PMID 33148167, 2020). "The results showed that HOMA-IR was negatively correlated with HK2, LDHA, PKM2, SIRT2, and lactic acid levels and had little correlation after RES intervention, which indicated that RES intervention promoted glycolysis by improving ovarian insulin resistance in PCOS rats." (PMID 36742000, 2022).
myeloma (17 papers, 2017 to 2025). "Additionally, aberrant activation of HK2 is linked to poor outcomes and PI resistance in myeloma patients." (PMID 40308607, 2025). "To better understand the impact of GLUT1 and HK2 downregulation in multiple myeloma pathogenesis, we determined the expression of both genes in multiple myeloma patients using the TT2 cohort." (PMID 36245401, 2023). "For example, in multiple myeloma cells, cyclin D1 promotes hexokinase 2 expression, a regulator of glycolysis in these cells." (PMID 38152849, 2023). "The expression of NEK2 and glycolysis-enhancing genes, such as hexokinase 2 (HK2), alpha-enolase (ENO1), and lactate dehydrogenase A (LDHA), was significantly increased in high-risk myeloma samples and positively correlated each other." (PMID 28086949, 2017). "Hypoxia-induced HK2 can enhance antiapoptotic effects in multiple myeloma via autophagy activation." (PMID 40170113, 2025). "Targeting HK2 has emerged as a promising treatment for myeloma." (PMID 40308607, 2025). "HK2, an isoform of hexokinase that is overexpressed in many malignancies including MM, is another promising target in myeloma given that small-drug inhibition of HK2 or knockdown of HK2 using anti-sense oligonucleotides kills neoplastic plasma cells with great efficacy." (PMID 35794249, 2022). "Using the MMRF CoMMpass study, we found that high GLUT1 and HK2 expression was correlated with poor overall survival in multiple myeloma patients (GLUT1: p = 0.022; HK2: p = 0.034)." (PMID 36245401, 2023). "This is mediated by hexokinase 2 (HK2), phosphofructokinase (PFK), pyruvate kinase M2 (PKM2) and lactate dehydrogenase A (LDHA) that are highly expressed in myeloma." (PMID 34768861, 2021). "Consistently, the expression of HK2, ENO1, LDHA, glucose transporter type 4 (Glut4), and monocarboxylate transporter 4 (MCT4) was downregulated in NEK2 silenced myeloma cells." (PMID 28086949, 2017). "In multiple myeloma, a negative 18F-FDG PET/CT scan was associated with low expression of hexokinase-2, whereas a positive scan is accompanied by high expression of proliferation genes or GLUT546." (PMID 38745021, 2024). "Aside from these technical issues, some patients with extensive bone involvement could have a negative result on 18F-FDG PET/CT because myeloma cells might have low expression of hexokinase-2, which is involved in the glycolysis of FDG in malignant cells." (PMID 34853295, 2021).
neuroblastoma (17 papers, 2016 to 2024). Neuroblastoma (NB) is the most common solid, extracranial childhood tumor. "Similarly, HNF4α has been shown to promote glycolysis, glucose uptake, lactic acid production and ATP levels in neuroblastoma cells, and the underlying mechanism involved hexokinase 2 (HK2) and Solute Carrier Family 2 Member 1 (SLC2A1) and the heterogeneous nuclear ribonucleoprotein U (hnRNPU)." (PMID 36249028, 2022). "Controversially, HK2 inhibition with 3-Bromopyruvate (3-BrPA) and autophagy induction with rapamycin decrease cell proliferation with apoptosis induction in neuroblastoma cell lines." (PMID 37887330, 2023). "The circRNA-ACAP2 promotes migration and invasion of neuroblastoma cells by miRNA-143-3p/hexokinase 2 signaling." (PMID 35847361, 2022). "It was reported that exosome-delivered circDLGAP4 elevated HK2 expression by sponging miR-143, and the increased HK2 further enhanced glycolysis in doxorubicin-resistant neuroblastoma cells." (PMID 35843942, 2022). "Both MYCN and hypoxia-inducible factor 1α (HIF-1α) are required for sustaining the aerobic glycolysis phenotype in neuroblastoma cells by transcriptional upregulation of glycolytic enzymes, including hexokinase 2 (HK2) and lactate dehydrogenase A (LDHA)." (PMID 36077650, 2022). "PDK1 and HK2 are involved in cell metabolism, which is known to be affected in neuroblastoma." (PMID 36831133, 2023). "In another study, it was reported that hepatocyte nuclear factor 4 alpha (HNF4A) and its derived long-noncoding RNA (HNF4A-AS1) promote aerobic glycolysis in neuroblastoma cells by upregulating HK2 and the major glucose transporter SLC2A1 (also known as GLUT1)." (PMID 36077650, 2022). "The expression of the PKM and HK2 genes strongly correlates with poor patient prognosis, suggesting that their products might confer a growth or survival advantage to neuroblastoma cells." (PMID 34847775, 2021). "For metabolic profiling of these conditions, we chose SHEP neuroblastoma cells, in which we had previously noticed MYCN-induced HK2 upregulation indicating metabolic reprogramming." (PMID 32346009, 2020). "Our data demonstrate that neuroblastoma and sarcoma cells are prone to aerobic glycolysis, which is partially mediated by the presence of VDAC bound HK-2." (PMID 29998379, 2018). "In neuroblastoma, lncRNA LINC01410 was found to upregulate radioresistance via miR-545-3p/HK2 axis." (PMID 35600868, 2022). "Given that the expression of PKM and HK2 in neuroblastoma samples is strong predictors of negative clinical outcome, analysis of the protein content of circulating EVs could be used as a prognostic indicator and a non-invasive method for stratification of neuroblastoma patients." (PMID 34847775, 2021).
esophageal cancer (15 papers, 2016 to 2025). A primary or metastatic malignant neoplasm involving the esophagus. "Thus, by combining metabolomics and transcriptomics, we have identified an aerobic glycolysis network that involves HK2 and glucose signaling associated with uncontrolled cell proliferation in early esophageal cancer development induced by dietary ZD." (PMID 29137232, 2017). "In an effort to investigate the role of lncRNA CASC7 and HK2 in our clinical centre, after the consent of the patients, we collected the surgical specimens of patients with oesophageal cancer (cohort 2)." (PMID 35474307, 2022). "To further explore how lncRNA CASC7 affects the process of glycolysis, we obtained from database (cohort 1) analysis that the expression level of lncRNA CASC7 was positively correlated with the expression level of HK2 in oesophageal cancer specimens." (PMID 35474307, 2022). "Next, we found that the expression of CASC7 and hexokinase 2 (HK2) in oesophageal cancer was positively correlated in database analysis, and this conclusion was further verified in cell experiments." (PMID 35474307, 2022). "In this study, we report the correlation between lncRNA CASC7 and HK2 in oesophageal cancer and their roles in this tumour." (PMID 35474307, 2022). "The chemoresistance to 5-FU and CDDP and the tumorigenesis of esophageal cancer stem cells are reduced after HK2 knockdown." (PMID 34858863, 2021). "HK2 has been proven to be involved in the progression of many tumours, including colon cancer, gallbladder cancer, glioma, myeloma, and pancreatic cancer, as well as oesophageal cancer, but the detailed mechanism needs to be further studied." (PMID 35474307, 2022). "However, there are few comprehensive studies on HK2 in esophageal carcinoma (ESCA) needs further study." (PMID 34708035, 2021). "Moreover, HK2 is required for the maintenance of esophageal cancer stem cell phenotypes." (PMID 34858863, 2021). "In oesophageal cancer cell lines, we showed that knockdown of lncRNA CASC7 decreased both the mRNA level and protein level of HK2." (PMID 35474307, 2022).
renal cell carcinoma (15 papers, 2014 to 2024). "We specifically explored the association of HK2 with the tumor stage, survival, immune cell infiltration, and prognosis in patients with renal cell carcinoma." (PMID 35265223, 2022). "Subsequently, Western blot and qRT-PCR were performed to analyze the protein and mRNA expression of HK2 in renal cell carcinoma tissues and cell lines." (PMID 35265223, 2022). "In the current study, we first analyzed the GEPIA database and found higher expression of HK2 in most cancers including renal cell carcinoma." (PMID 35265223, 2022). "Keeping in mind the important role of HK2 in cellular metabolism, we sought to explore its function in immune cell infiltration and prognosis of renal cell carcinoma." (PMID 35265223, 2022). "Further analyses confirmed the positive correlation of HK2 with immune cell infiltration in renal cell carcinoma tissues." (PMID 35265223, 2022). "Predominantly, HK has two isoforms HK1 and HK2; the former is widely expressed in adult normal tissues, and the latter is overexpressed in a variety of cancers including renal cell carcinoma." (PMID 35265223, 2022). "The analysis of RNA-seq data revealed a high expression of HK2 in renal cell carcinoma; furthermore, Western blot and qRT-PCR also showed high expression of HK2 in renal cancer tissues and cell lines." (PMID 35265223, 2022). "the expression of HK2 is positively correlated with the immune cell infiltration and prognosis of renal cell carcinoma patients, thus playing an important role in renal cancer development." (PMID 35265223, 2022). "Furthermore, the HK2 expression was positively correlated with lymph node metastasis, histopathological grade, and tumor stage in renal cell carcinoma patients." (PMID 35265223, 2022). "Interestingly, miR-145 directly binds to HK2 mRNA and reduces its expression in renal cell carcinoma." (PMID 34858863, 2021). "Moreover, it was reported that the mammalian target of rapamycin (mTOR) activation is important for the betulin‐induced cytotoxicity in renal cell carcinoma, as mTOR increased pyruvate kinase muscle isozyme M2PKM2 and hexokinase 2 (HK2) expression by upregulating the aerobic glycolysis." (PMID 39723067, 2024).
viral infection (15 papers, 2015 to 2025). "Previous studies have shown that lactate is critical for blocking RLRs signalling associated with viral infection, and that HK2 can influence the activation of RLRs signalling by regulating lactate production." (PMID 36059492, 2022). "In addition to glycolytic enzyme activity, HK2 also participates in the progression of autophagy and manages the innate immunity caused by viral infection through autophagy." (PMID 40170113, 2025). "Glycolysis is the first metabolic pathway to be elucidated, and many studies have shown that glycolysis and its key enzyme HK2 play important roles in viral infection." (PMID 40170113, 2025). "Our findings provide evidence that FMDV is closely correlated with host metabolism, increasing the understanding that glycolysis and HK2 facilitate virus infection, and provide new ideas for further elucidating the pathogenic mechanism of FMDV." (PMID 40170113, 2025). ", we next assessed how IRF5 controls gene expression of Hk2 and other key metabolism enzyme genes upon viral infection in vivo." (PMID 33423291, 2021). "Using a mouse model of influenza A infection, we have shown that Hk2 gene expression is controlled by IRF5 during viral infection and gene expression levels are decreased in the absences of IRF5." (PMID 33423291, 2021). "Testing HK2 dispensability in the context of other viral infections, other immune cell types, and tumor immunity would be important steps to making more generalizable conclusions." (PMID 30140438, 2018). "This hypothesis suggests that HK2-driven aerobic glycolysis supports viral infections by providing energy and biomolecules for replication, as well as by providing lactate as a metabolite to evade host defense." (PMID 37939149, 2023). "Finally, CD4 T cell mediated immuno-inflammatory responses to a virus infection were similar between WT and HK2 KO animals." (PMID 29352298, 2018). "Our data elucidate a novel role for HK2 in cellular stress response and viral infection that could be exploited for therapeutic intervention." (PMID 26247723, 2015). "Other genes that were down-regulated with viral infection (GOLGA2, IFI16, WDR81, HK2, SQSTM1, ULK1) remained down-regulated with NIC treatment (with and without virus)." (PMID 37901834, 2023). "During the viral infection, RIG-I-MAVS hijacks HK2-MAVS, thus impairing the normal glycolysis process." (PMID 34917069, 2021). "Thus, long noncoding RNAs may also inhibit viral replication by disrupting HK2, voltage-dependent anion channel (VDAC), and MAVS ternary complex to inhibit glycolysis in viral infection." (PMID 34917069, 2021). "Interestingly, knockdown of HK2 did not simulate the effect of lonidamine but instead inhibited the M1 virus infection." (PMID 33292203, 2020). "The observations that the expression of HK2 appears non-essential for CD4 T cell responses against virus infections is of interest since it suggests that targeting HK2 for cancer therapy may not have untoward effects on CD4 T cell mediated immune response against virus infections." (PMID 29352298, 2018). "Though we used HK2 and LC3 as measures of CDK8/19-dependent metabolic gene expression during DENV2 infection, these are likely not the only genes regulated by CDK8/19 during viral infection." (PMID 32560467, 2020). "While our results indicate that TNFα induces HK2 expression, which we found to be important for TNFα-induced glycolytic activation, its deletion did not impact the TNFα-mediated induction of the UDP-glucose pool, nor did it restore viral infection in the face of TNFα treatment." (PMID 35834576, 2022).